IL6 (interleukin 6)
Diseases named in the same sentence as IL6 in open-access papers (continued):
Sharing a sentence is not in itself a finding about the gene and the disease.
cancer (continued). "In particular, G-CSF, GM-CSF and IL-6 secreted by cancer and/or by stromal cells surrounding cancer cells induce potent activation of G-MDCs by activating the myeloid transcription factor C/EBPβ." (PMID 34674757, 2021). "Taken together, these data unequivocally confirmed that CAFs-secreted IL-6 induced LRG1 expression through downstream activation of JAK2/STAT3 signaling in cancer cells." (PMID 34930899, 2021). "In ovarian cancer, adipocytes express IL-6, increasing the expression of BCLxl that provides the ability to cancer stem cells to become resistant to drug therapy." (PMID 33920983, 2021). "We used RT-qPCR to screen mRNA levels of a variety of inflammatory factors closely related to the development of cancer, including IL-6, IL-10, IL-17A, and Hsp90α, in LINC00673 and control stable cells." (PMID 34094965, 2021). "Previously, dexmedetomidine was found to significantly suppress TNF- α and IL-6 levels in patients undergoing laparoscopic ovarian resection for cancer." (PMID 34692497, 2021). "TGF-beta production by TILs downregulates the expression of T-cell IL-6 and prevents cancer progression." (PMID 33923292, 2021). "CAFs in human clinical PDAC are known to be heterogeneous, including the αSMA-positive myCAFs located adjacent to the ductal glands and IL-6-positive iCAFs located apart from the cancer cells." (PMID 33633222, 2021). "That stromal CAFs and IL-6 inhibit autophagy in cancer cells was further confirmed in an experimental model of CCA resembling human liver fluke-induced cholangiocarcinogenesis." (PMID 33925189, 2021). "The pro-oncogenesis effects of IL-6 have been demonstrated in various cancer types, including lung cancer, breast cancer and colorectal cancer, among others." (PMID 33429846, 2021). "sGP130 inhibits IL-6 trans-signaling, which is enabled by sIL-6R and is known to facilitate inflammation and have a role in cancer." (PMID 34183723, 2021). "Another pro-tumorigenic cytokine found in the TME is interleukin-6 (IL-6), which can be secreted by both fibroblasts and cancer cells." (PMID 33758206, 2021). "We demonstrate that the cognitive functions and survival rates in cancer patients depend on the apoptotic signaling pathways via the critical communication and IL-6 landscapes of stimulated CTCs." (PMID 34669701, 2021). "A mechanism whereby PDS5B depletion promotes proliferation of cancer cells is possible through the IL-6/STAT3/cyclin D axis." (PMID 34070827, 2021). "In support of this, we show that cancer cells deprived of extracellular citrate for 48 h release IL-6, which stimulates angiogenesis and GROs involved in stromal transformation/senescence." (PMID 33758075, 2021). "Both activated adipocytes and cancer cells secrete IL-6, which is considered a strong lipolytic factor that induces the release of FAs from adipocyte triglyceride stores." (PMID 34722305, 2021). "A few other studies also suggest targeting the TGF-β-IL-6 axis to arbitrate the resistance mechanism of cancer cells for better molecular therapy." (PMID 34336101, 2021). "By coculturing adipocytes with cancer cells, a surge in the levels of different proteases and cytokines (such as IL-6 and IL-1β) and a reduction in adipocyte-related markers are observed." (PMID 34202411, 2021). "The overall survival analysis was performed stratifying the cancer samples of each TCGA cohort based on the expression mean value of IL6, IL6R, and IL6ST by using UCSC Xena tool." (PMID 34576335, 2021). "High IL-6 levels induce tumorigenesis and are regulators of angiogenesis, invasiveness, metastasis, apoptosis and cancer cell survival." (PMID 34445479, 2021). "IL-6 can regulate the crosstalk between CSCs and cancer cells through constitutive activation of Stat3, and Stat3 regulates the expression of Oct3/4, which is a major reprogramming factor known to induce the expression of various stemness genes." (PMID 33804152, 2021).
cancer (continued). "The results reveal different networks in each group with IL-10 and Rantes/CCL5 clusters on control samples and GMCSF and IL-6 in cancer." (PMID 35048057, 2021). "p65 O-GlcNAcylation at Thr-322 and Thr-352 also enhances DNA binding to the promoters of IL-6, TNF-α, and MCP1 which contributes to the development of colitis and colitis-associated cancer." (PMID 34722537, 2021). "The association between IL‐6 and JAK2, and STAT3 signalling pathway activation and cancer cell migration was observed in a paracrine or autocrine IL‐6‐rich inflammatory environment." (PMID 33759378, 2021). "One of these cytokines, IL-6, is considered a key regulator of HCC, with its high levels associated with this cancer progression." (PMID 34203215, 2021). "Depletion of PDS5B in cancer cells induces secretion of interleukin-6 (IL-6), which binds to its receptor and in turn activates intracellular STAT3." (PMID 34070827, 2021). "These cancer-related cognitive changes (CRCC) are regulated by an adverse biological process involving cancer stem cells (CSCs) and IL-6." (PMID 34669701, 2021). "In preliminary experiments, we explored the polarizing activities of IL-6, another cytokine present in cancer patients, as compared to TGFβ." (PMID 34638439, 2021). "A growing body of evidence demonstrates that pro-inflammatory cytokines such as interleukin-6 (IL-6) are present with high levels in cancer cells." (PMID 33478512, 2021). "A co-culture of primary squamous lung carcinoma cells with MSCs led to the secretion of CCL3 by cancer cells and an elevated expression of IL-6, CCL2, ICAM-1, and VCAM by MSCs." (PMID 34950592, 2021). "In conclusion, we show an important mechanism between PSC-cancer cell interaction involving ATP and IL-6, activating P2X7 and IL-6 receptors, respectively, both potential therapeutic targets in PDAC." (PMID 34440697, 2021). "Type I interferon, IL-6, and IL-17 promote the up-regulation of immunosuppressive molecular and accumulation of immunosuppressive cells in cancer." (PMID 33679751, 2021). "Although the pleiotropic cytokine IL6 is involved in multiple physiological functions, it is also relevant to inflammatory diseases and cancer." (PMID 34576335, 2021). "It is well-established that CAFs are the main source of IL-6 in TME in different types of tumors 97-99, indicating a potential link between CAFs and cancer cachexia through the production of IL-6." (PMID 34373744, 2021). "The activated p70S6 kinase is reported to boost cancer metastasis and invasion through IL-6 mediated EMT in squamous cell carcinoma." (PMID 34588926, 2021). "Several studies have reported that cytokines such as IL-6, IL-8, IL-10, TGF-β, and TNF-α are detected in cancer-associated exosomes, leading to cancer progression and drug resistance." (PMID 34771423, 2021). "During hypoxia, STAT3 is activated in cancer cells by ROS, mTORC1, and/or IL-6, and further induces HIF-1a." (PMID 34440220, 2021). "To further confirm the ultrastructure of Rab37-mediated vesicle recruitment of IL-6, we performed immuno-transmission electron microscopy on cancer CM treated THP-1 human monocyte cells." (PMID 34093869, 2021). "There are a few studies that have analyzed the kinetics of CRP, PCT and IL-6 in pediatric cancer patients with fever." (PMID 34828740, 2021). "Our in vitro investigation shows that the levels of IL-6 mRNA in cancer cell treated with Mn-CDs-NHF are significantly reduced relative to Gadovist-treated cells." (PMID 34834397, 2021). "IL-6 is a cytokine that plays an important role in acute-phase response, inflammation, hematopoiesis, and progression of cancer, and performs the body’s defense function against antigens introduced from the outside." (PMID 34558607, 2021).
cancer (continued). "The pattern with low IL-6 in the stroma and high LC3/high p62 in cancer cells (violet line; L/H/H; HR: 1.659, 95% CI: 0.813–3.384) also showed a good prognosis when compared with the other patterns having high IL-6 and/or low LC3 expression." (PMID 33925189, 2021). "Although this study is contradictory to previous results, there is solid experimental evidence supporting that IL-6 mediated EMP promotes resistance to therapies in cancer." (PMID 34361105, 2021). "IL-6 is a pleiotropic cytokine and plays a major role in angiogenesis, cancer cell survival, chemotherapy resistance and development of liver metastases." (PMID 34200156, 2021). "In previous studies, serum IL-6 level has shown an inverse correlation with the survival of cancer patients." (PMID 34239594, 2021). "IL-6 delivers signals through the STAT3 pathway, and recent studies have reported that CD36 is a downstream target of activated STAT3, suggesting that upregulation of IL-6 expression would further increase the uptake of FAs by cancer cells." (PMID 34722305, 2021). "Regarding angiogenesis, STAT3 is activated in cancer cells by reactive oxygen species (ROS), mechanistic target of rapamycin complex 1 (mTORC1) and/or IL-6, and further induces hypoxia-inducible factor 1-alpha (HIF-1a) activation during hypoxia." (PMID 34440220, 2021). "SIR is characterized by an increase in concentration of inflammatory factors, such as CRP, TNF-α, IL-1, IL-6, INF-γ, and PIF (previously known as “cancer cachectic factor” or cachexia-associated protein)." (PMID 33557173, 2021). "The inflammatory response from cancer cells promotes the infiltration of neutrophils, which benefits cancer progression via the secretion of IL-2, IL-6, IL-10, TNFα, and VEGF." (PMID 34503128, 2021). "Interleukin-6 (IL-6) has been shown its significant characteristics in the pathological processes of inflammation, autoimmunity, and a series of cancers since its identification in the 1980s." (PMID 34568032, 2021). "NF-κB is an essential transcription factor for inflammatory responses, and is one of the most important molecules linking chronic inflammation to cancer, upstream of IL6 release." (PMID 34831016, 2021). "The administration of alpha-tocopherol (vitamin E), plant-derived glycoprotein (UDN glycoprotein), and isoliquiritigenin originated from licorice root downregulates IL-6 signaling in several cancers." (PMID 33923292, 2021). "This agent is a third-generation selective estrogen receptor modulator (SERM) that shows an inhibitory effect on IL-6/GP130 in several cancers including GBM initiation and progression." (PMID 34948224, 2021). "We found that the IL-6- and IL-1B-encoding genes were dramatically overexpressed in CD4+ T cells due to exhaustion induced by cancer cells." (PMID 34439305, 2021). "Several studies have investigated the ability of IL-6/GP130 to promote chemotherapy resistance in several cancers as IL-6 is known to bind to the extracellular surface receptor glycoprotein 130 (GP130) and activate cell survival-related pathways." (PMID 34445405, 2021). "Cytokine release results showed that numerous inflammatory cytokines-chemokines related to cancer initiation and development, such as IL-8, IL-6, VEGF, MCP1, TNF-α were significantly increased in LIN28B-overexpressing MMNK-1 cells." (PMID 34837926, 2021). "Among them, the abundance of Corynebacterium_1 was previously demonstrated to be correlated with serum concentrations of interleukin-6 and C-reactive protein in cancer patients." (PMID 34220499, 2021). "The median ALC and lymphocyte subsets (CD3, CD4, CD8, Treg, NK and B cells) were significantly lower in cancer patients, while median fibrinogen levels (p < 0.001) and IL‐6 (p < 0.001) were significantly higher in cancer cohort." (PMID 34786866, 2021). "Substantial evidence demonstrates the important role of IL-6 in the niche microenvironment to guide the metastatic process in cancer." (PMID 33613850, 2021).
cancer (continued). "Several research articles from our group have shown that IL-6 levels in advanced cancer patients correlate with leptin, the main marker of body composition and nutritional status." (PMID 33809200, 2021). "Leukemia Inhibitory Factor (LIF) and its receptor (LIFR), part of the interleukin-6 (IL-6) cytokine family, make up one such ill-defined piece of the puzzle connecting inflammation to cancer." (PMID 34395259, 2021). "Previous studies have shown that IL-6 augments cancer chemotherapeutic resistance through activation of the NF-κB κ and STAT3 signaling pathways." (PMID 34131122, 2021). "IL-6 signaling can thereby contribute to multiple aspects in the process of malignant progression, promoting cancer cell growth and enhancing the metastatic niche." (PMID 33651821, 2021). "As mentioned in the previous section, IL-6 has been associated with EMT and metastasis in different cancers." (PMID 34572947, 2021). "In agreement with the present findings, BRG1 was found to promote TXNIP, CXCL11 and IL6 expression in GBM cancer stem cells, suggesting a broad role of these genes in the pro‐tumorigenic role of BRG1 in GBM." (PMID 33528916, 2021). "Angiogenic factors including GM-CSF, IL-8, CSF, VEGF, and monocyte chemotactic protein-1 (MCP-1) induced by IL-6 lead to cancer cell invasion in in vitro conditions." (PMID 33917793, 2021). "IL-6 is crucial in KRAS driven PDAC development and progression from PanIn lesions to invasive cancer and promotes cell viability and invasion, underlining its metastatic potential." (PMID 32940862, 2021). "After activation of the CD40 receptor, cancer cells release IL-8, IL-6, or TNF, which consequently increases the T-cell-dependent antitumor immune response." (PMID 34441316, 2021). "Vascular CAFs (vCAF), the most abundant population, were found to secrete IL6 to promote self-renewal of cancer cells." (PMID 34760886, 2021). "The IL6/JAK/STAT3/SIGNALING pathway has been proved that it was aberrantly hyperactivated in various types of cancer and had a strong relationship with poor clinical prognosis." (PMID 34712264, 2021). "Interleukin IL-6 is produced by tumor cells, and an elevated level of IL-6 has been reported in various cancer types, such as lung cancer, renal cell carcinoma, and ovarian cancer." (PMID 33969006, 2021). "In preclinical models, antibody administration against IL-6 or IL-6 knockout prevents cancer cachexia, although anti-inflammatory treatments have shown less positive outcomes in human trials." (PMID 33801684, 2021). "For instance, IL6 induces numerous cancer-promoting changes through STAT3, while IL27 or OSM can induce an opposing effect through the related signal transducer STAT1, also activated as part of the JAK/STAT pathway." (PMID 34834425, 2021). "Our data also clearly demonstrated that ZO essential oil reduced IL-6 levels in the culture supernatants of the cancer cells." (PMID 34371622, 2021). "Because of the crucial role of IL-6 in cancer development, targeting the IL-6 pathway has been proposed to be a potent therapeutic approach." (PMID 34671021, 2021). "As already reported in many types of cancer, IL-6/JAK/STAT3 signaling is also significantly hyperactivated in the subset of ONB patients with a poor clinical prognosis." (PMID 34064009, 2021). "IL6 participates in the recruitment and polarization of macrophages, natural killer cells, and T cells, promoting immune control of cancer cells." (PMID 34073987, 2021). "IL-6 directly stimulates the proliferation and survival of cancer cells by stimulating the advancement of the cell cycle, the expression of anti-apoptotic molecules and angiogenesis." (PMID 35096626, 2021). "Translational repression of CYP3A genes, by the pro-inflammatory cytokine interleukin-6 (IL-6) and tumor necrosis factor α (TNF-α) have been suggested as the mechanisms causing decreased CYP3A-activity in cancer patients." (PMID 34572915, 2021).
cancer (continued). "IL-6 has the potency to contribute to the angiogenesis in cancer and chronic inflammatory diseases according to recently published results." (PMID 33435569, 2021). "Imbalanced mitochondrial production and degradation was found in the skeletal muscle of cancer cachexia, in which IL-6 overexpression in this tissue diminished mitochondrial content but simultaneously elevated the expressions of PGC-1α and Mfns." (PMID 33513795, 2021). "On the contrary, M2 macrophages can provide a nutritional advantage to cancer cells when stimulated by IL-4, IL-6, IL-10, IL-13, transforming growth factor β (TGF-β), vascular endothelial growth factor (VEGF) and other M2-specific cytokines." (PMID 34717710, 2021). "In cancer, IL-6 and STAT3 are related to the induction of senescence and in lung fibroblasts, STAT3 is an important factor driving oxidant-induced senescence." (PMID 34207510, 2021). "RT2 Profiler PCR array for cancer related genes also showed upregulation of several other inflammatory genes including IL-6, CCL4, MCP-1, etc.." (PMID 34900746, 2021). "Although many studies have shown the involvement of IL-6 in skeletal muscle atrophy due to systemic inflammation in cancer patients, little is known about the intracellular mechanisms regulated by this cytokine in skeletal muscle cells." (PMID 34944037, 2021). "The neutrophil ratio, C-reactive protein (CRP), procalcitonin (PCT), white blood cells (WBCs), and IL-6 have been extensively studied as markers of long-term prognosis in many cancers." (PMID 34956932, 2021). "IL-6 can also act on cancer cells in autocrine manner as a growth factor and in paracrine fashion activating inflammatory surrounding cells." (PMID 33216184, 2021). "IL-6 is overexpressed in the TM and stimulates the JAK/STAT3 pathway, which is a molecular event that is associated with poor prognosis for cancer patients." (PMID 34440220, 2021). "Given how frequently rapid induction of IL-6 was observed in cancer cells, the current concept that pro-tumorigenic activities of the pathway would be limited to its chronic engagement clearly needs revision." (PMID 35087822, 2021). "A preclinical investigation demonstrated that EGFR-TKI administration not only decreased the viability of cancer cells, but also increased IL-6 production from cancer cells." (PMID 33466795, 2021). "IL-6 has been considered a keystone cytokine in the link between inflammation and cancer, and has received a lot of attention as a potential therapeutic target." (PMID 34361105, 2021). "In clinical practice, high levels of IL-6 predict chemotherapy resistance and poor prognosis in many type of cancers." (PMID 35096626, 2021). "Our results on IL6R methylation deserve further validations studies to fill this current gap in the literature concerning cancer, IL6 signaling, and its epigenetic regulation." (PMID 34576335, 2021). "HGF promotes cancer stemness and increases the clonogenicity, whereas IL-6 mainly contributes to enhance the invasion of CMS2 CR-CSphCs." (PMID 34408135, 2021). "We believe that IL-6 and IL-6-related signaling differ greatly from the routinely used biomarkers in cancer research." (PMID 34681685, 2021). "Further, IL-6 directly inhibits the IRF3/IFN-β arm of STING signaling in selected cancer cells, alleviating the tumor suppressive effects of the pathway in vivo." (PMID 35087822, 2021). "It has recently been reported that cancer cells polarize macrophages into the M2 phenotype in co-culture, and such phenotype changes make macrophages secrete IL-6, which promotes peritoneal dissemination." (PMID 33509150, 2021). "In terms of cancer research, different case-control studies have suggested the association of IL1A, IL2, and IL6 with CRC." (PMID 34931923, 2021). "Multiple drug resistance has been observed when IL-6 is highly expressed by cancer cells, suggesting the role of cytokines in cancer cell evasion to drug-induced cell death." (PMID 34307156, 2021).